RAF1 (Raf-1 proto-oncogene, serine/threonine kinase)
Diseases named in the same sentence as RAF1 in open-access papers (continued):
Sharing a sentence is not in itself a finding about the gene and the disease.
breast cancer (continued). "In addition, several disease pathways including the ‘endometrial cancer, ‘colorectal cancer’, ‘ErbB signaling’, ‘breast cancer’, and ‘gastric cancer’ pathways with Kras, Gsk3b, and Raf1 genes were significantly enriched." (PMID 37505851, 2023). "Also, Hb% and RAF-1 levels were significantly decreased in breast cancer patients as compared with healthy control." (PMID 34837907, 2021). "So, the MiR-106a gene may serve as a potential genetic noninvasive biomarker in breast cancer patients, through regulating RAF-1 expression." (PMID 34837907, 2021). "In particular, and in accordance with the interactions presented in this work, RAF1 targeting by miR-497 inhibits breast cancer cell growth, whereas downregulation of miR-424 leads to aberrant cell proliferation through MEK1 (MAP2K1) upregulation in senile hemangioma." (PMID 31976858, 2020). "This study provides a totally new and scientific way to holistically decipher that the pharmacological mechanisms of Damnacanthus indicus C.F.Gaertn in the treatment of breast cancer might be associated with MAP2K1, PIK3CA, and Raf1 genes." (PMID 30906409, 2019). "Anandamide inhibits adenylyl cyclase (AC) and thus activating the Raf-1/ERK/MAP pathway in ER+/PR+ breast cancer cells whilst THC activates the transcription factor JunD to finally execute action towards apoptosis in ER−/PR+ breast cancer cells." (PMID 25115386, 2014). "In breast cancer cell lines, FW-04-806 inhibits cell proliferation, caused G2/M cell cycle arrest, induced apoptosis, and downregulated Hsp90 client proteins HER2, Akt, Raf-1 and their phosphorylated forms (p-HER2, p-Akt) in a dose and time-dependent manner." (PMID 24927996, 2014). "In this study we employed a metastatic breast cancer xenograft model harboring constitutive activation of Raf-1 oncogenic signaling to investigate the mechanistic linkage between aberrant MAPK activity and development of endocrine resistance through abrogation of the ERα signaling axis." (PMID 24816249, 2014). "They further revealed that targeting EZH2 downstream activation pathways such as RAF1-ERK signaling with the MEK inhibitor AZD6244 could prevent breast cancer progression by eliminating CSCs." (PMID 25051981, 2014). "Notably, total and nuclear β-catenin levels were not reduced by ERK inhibition in HCC cells, an observation which contrasts with a previous study showing that the RAF1-p-ERK-β-catenin pathway is required for expansion of breast cancer-initiating cells and enhanced cancer malignancy." (PMID 26517516, 2015). "For example, in breast cancer cells, PDE8A forms a complex with Raf-1 at the plasma membrane, generating a local microdomain with reduced cAMP levels." (PMID 41601682, 2026). "To further explore this mechanism, we examined the ability of KBU2046 to suppress Raf1 and ERK1/2 phosphorylation in breast cancer cells." (PMID 39449805, 2024). "It was found to promote cellular senescence in breast cancer, to reduce the expression of MMP-9 and limit the invasion of human glioblastoma and breast cancer cell lines via inhibiting the Ras/Raf-1/ERK/AP-1 pathway." (PMID 37506102, 2023). "SRGAP3 has been implicated as a potential oncogenic driver in low-grade gliomas, when fused with RAF1, resulting in constitutive activation of the ERK/MAPK pathway, and altered expression of the SRGAP protein has been demonstrated in breast cancer." (PMID 33431066, 2021). "Phloroglucinol, isolated from the brown alga E. cava, diminished the population of breast cancer cell lines (MCF7, SKBR3 and BT549) in tumors, by inhibiting KRAS and its downstream PI3K/Akt and RAF-1/ERK signaling pathways." (PMID 33007997, 2020). "In breast cancer (BC) cells, EZH2 promotes expansion of TICs and mammosphere formation through activation of RAF1/β-catenin signaling, while in glioblastoma loss of H3K27me3 can lead to aberrant Wnt signaling activation, which is necessary for maintenance of CSCs." (PMID 33322354, 2020).
breast cancer (continued). "The same research group also confirmed the effectiveness of phloroglucinol against metastasis of breast cancer through downregulation of SLUG by the inhibition of PI3K/Akt and RAS/RAF-1/ERK signaling pathways." (PMID 33007997, 2020). "To investigate new therapeutic strategies for treatment-resistant breast cancer, we explored treatment targets using multigene panels, which showed high expression of HIF1A, RAF1, AKT2 and VEGFA in two TNBC cases." (PMID 31018595, 2019). "Extracellular-regulated kinase (Erk) is a member of the mitogen-activated protein kinase (MAPK) signal-transducing family, which consists of three key cascades, termed Raf-1, Erk and p38 MAPK, with Erk being the most relevant factor in breast cancer." (PMID 25789027, 2015). "Constitutive activation of Raf-1 oncogenic signaling induced HER-2 overexpression and resulted in the development of distant metastases in ERα+ MCF-7/ΔRaf-1 breast cancer xenografts." (PMID 25051360, 2014). "Recently, it has been shown that there is a Raf-1-mediated involvement of Aurora-A kinase signaling which is important in regulating the balance between EMT and MET in ER+ breast cancer cells." (PMID 25051360, 2014). "Meanwhile, upregulation of miR-195 expression has been shown to suppress cell proliferation and invasion by targeting the Raf-1 and Ccnd1 genes in both ZR-75-30 and MCF7 human breast cancer cells." (PMID 24402230, 2014). "ER2 (-) and PR (±) breast cancer cases with RAF1 protein and mRNA high or low expression were not related to survival." (PMID 38356266, 2024). "The present work provides a novel extracted peptide, H-P, which can modulate the Raf-1 signaling pathway, the autophagic machinery, and the expression of NF-kB effectors in breast cancer cells without any cytotoxic effect in the normal mammary cells." (PMID 34513674, 2021). "Additionally, a quantitative proteomics analysis of CY-9d-treated breast cancer cells revealed some potential Raf1 and ERK1 interacting proteins in breast cancer cells, such as HSP90, PAK4 and RAB2A." (PMID 29262632, 2017). "Finally, some potential Raf1 and ERK1 interacting proteins in breast cancer cells were detected, such as HSP90, PAK4 and RAB2A." (PMID 29262632, 2017). "Previous studies have shown that ectopic expression of miR-195 also sensitized glioblastoma, hepatocellular carcinoma, breast cancer, and colon tumor cells to temozolomide, 5-fluorouracil, adriamycin, and doxorubicin treatment by targeting BCL2L-2, BCL-W, and RAF-1 genes, respectively." (PMID 29126391, 2017). "In addition, miR-133a targeting of EGFR, miR-200c and miR-30c targeting of KRAS, miR-148b targeting of NRAS, miR-7 targeting of RAF1, miR-206 targeting of RASA1 and miR-21 targeting of SPRED1 have been reported in breast cancer cells." (PMID 27462780, 2016). "To confirm the molecular mechanisms underlying the antimetastatic effects of BRACs, we investigated whether treatment with BRACs inhibited the mRNA expression of raf1, mek, and jnk in HER2+ breast cancer cells." (PMID 26649302, 2015). "Similar inhibition has been reported for other tissues and cells, such as AKT-induced phosphorylation of Raf-1 at Ser259 by insulin-like growth factor 1 in MCF-7, a human breast cancer cell line and by platelet-derived growth factor in vascular smooth muscle cells." (PMID 26442853, 2015). "Furthermore, the methylation state of CpG islands in the promoter region upstream of the miR497-195 cluster was responsible for the down-regulation of those two miRNAs in breast cancer, and direct targets of miR-195-5p included CCND1 and RAF1." (PMID 25888956, 2015). "Among breast cancer cell lines, MCF7 is unique when the measure crs(h = 2) is used to assess the EGFR pathway with GRB2 and MAPK1 ranking highest, while all the other cell lines have EGFR and/or RAF1 as top ranking genes." (PMID 24550933, 2014).
breast cancer (continued). "Here, DBA identified candidate rearrangements of RAF1 in lung cancer (DMS-153), pancreatic cancer (PL5), anaplastic astrocytoma (D538-MG), and osteosarcoma (CAL-72), and candidate rearrangements of BRAF in gastric cancer (NCI-N87), breast cancer (HCC38), and glioblastoma (D397-MG)." (PMID 23637631, 2013). "Cases with high RAF1 mRNA expression had a lower distant metastasis-free survival in HER2 (-) breast cancers (p = .011), while HER2(+) breast cancer was not related to the distal metastasis-free survival (p = .066)." (PMID 38356266, 2024). "Collectively, these findings suggest that H-P-mediated Raf-1, MEK1/2, LC3B, and NF-kB provide a novel and efficacious multikinase inhibitor for treating breast cancer without detectable cytotoxic effects." (PMID 34513674, 2021). "A phosphoproteomic study defining breast cancer subtypes by non-negative matrix factorization (NMF) applied to genomic, transcriptomic, and proteomic data showed high levels of phosphorylated RAF1 and ARAF (considered surrogates of kinase activation) in Basal-I and HER2-I subtypes, respectively." (PMID 36358725, 2022).
Noonan syndrome (75 papers, 2008 to 2025). "Rare pathogenic variants in the PTPN11, KRAS, SOS1 and RAF1 genes are the main molecular causes of Noonan syndrome (NS)." (PMID 40041314, 2025). "Pathogenic RAF1 mutations in the Cr2 domain causing Noonan syndrome are mainly associated to the onset of cardiovascular malformations, although sporadic cases of cerebrovascular abnormalities have been reported." (PMID 38874808, 2024). "Unexpected finding was observed in SOS1 and RAF1 genes which are both reported to be associated with 10–20% of Noonan syndrome cases, and were observed at lower detection rate of 6% each in the current study." (PMID 37815686, 2024). "Lethal induction of labor was also demanded because of RAF-1 gene mutation to indicate the possibility of Leopard spot syndrome and Noonan syndrome." (PMID 37231382, 2023). "Mutations in 16 genes, including PTPN11 (50%), SOS1 (20%) and RAF1 (5%–15%), have been linked to the development of Noonan syndrome." (PMID 37525886, 2023). "This is the first case of Noonan syndrome complicated with cerebral haemorrhage caused by RAF1 gene mutation in neonates." (PMID 35953836, 2022). "Noonan syndrome (NS) is a dominant autosomal disease, caused by mutations in genes involved in cell differentiation, growth and senescence, one of them being RAF1 mutation." (PMID 35950157, 2022). "The RAF1:p.Ser257Leu variant is associated with severe Noonan syndrome (NS), progressive hypertrophic cardiomyopathy (HCM), and pulmonary hypertension." (PMID 35052347, 2021). "Case variant PTPN11 p.(Asp61Gly) is a known causal variant for Noonan syndrome, and RAF1 p.Pro261 is a hotspot for multiple gain-of-function mutations, including p.(Pro261Thr), causing Noonan syndrome." (PMID 33971972, 2021). "Other known Noonan-syndrome-associated genes include RAF1, RIT1, KRAS, NRAS, SHOC2, BRAF, MAP2K1, and CBL." (PMID 34828352, 2021). "A recent report identified that a mouse model for the Noonan syndrome mutation RAF1-L613V exhibits an increased GFAP expression in the cortex and hippocampus." (PMID 34222248, 2021). "LEOPARD and Noonan syndromes were already associated in ClinVar with 6 and 28 pathogenic RAF1 variants, respectively." (PMID 32858845, 2020). "Overall, the heterozygous RAF1 p.Ser259Tyr variant identified by WES confirms the diagnosis of Noonan syndrome in our patient." (PMID 31030682, 2019). "Gain-of-function mutations in RAF1 were identified in 3–17% of patients with Noonan syndrome and two patients with Noonan syndrome with multiple lentigines." (PMID 31030682, 2019). "Here, we describe the cellular and behavioral consequences of a mutation in a gene called Raf1 that is associated with a common RASopathy, Noonan Syndrome." (PMID 31017896, 2019). "In a case series study reporting 212 newborns with clinical suspicion of Noonan syndrome and related disorders, the RAF1; p.Ser259Tyr mutation was reported in one patient with Noonan syndrome." (PMID 31030682, 2019). "In conclusion, WES allowed us to identify a de novo p.Ser259Tyr mutation in RAF1 and to provide a definite diagnosis of Noonan syndrome." (PMID 31030682, 2019). "The phenotype-genotype correlation between Noonan syndrome and the RAF1 mutation were previously reported, and the two patients in our cohort with the p.R391S mutation had typical features of Noonan syndrome." (PMID 29402968, 2018). "Additionally, Pompe disease with GAA mutations and Noonan syndrome with RAF1 mutations are common secondary causes of HCM." (PMID 38165464, 2024). "Mutated RAF1 is less common in human cancers but mutation in RAF1 may lead to Noonan syndrome which is a disorder that includes short stature, facial dysmorphology, and congenital heart defects." (PMID 38216592, 2024). "Notably, pathogenic variants in RAF1 are associated with Noonan syndrome, a genetic disorder characterized by short height, congenital heart disease, bleeding problems, and skeletal malformations." (PMID 37569667, 2023).
Noonan syndrome (continued). "This was a female neonate with confirmed RAF1 mutation (Noonan syndrome)." (PMID 34446079, 2021). "Approximately 91% of RAF1 variants are associated with Noonan syndrome (Search by Disease)." (PMID 31030682, 2019). "Indeed, biventricular hypertrophy has been noted in patients with Noonan syndrome carrying RAF1 mutations." (PMID 31030682, 2019). "RAF1 is a known morbid gene associated with Noonan syndrome (OMIM: 611553)." (PMID 30359267, 2018). "In any case, the cancer-associated mutations of the 14-3-3 binding motif surrounding S365 represent an interesting parallel to the Noonan-Syndrome associated RAF1 mutations, affecting the equivalent motif around S259 in Raf-1, and the cancer-associated mutations in the CR2 of A-Raf." (PMID 27034005, 2016). "In addition, RAF1 exon 7 was sequenced since activating mutations in this exon has been described in the Noonan Syndrome." (PMID 21533174, 2011). "Multiple gene variants can cause Noonan Syndrome/NSML, including PTPN11, BRAS, and RAF1, with PTPN11 variants being the most common one." (PMID 39898109, 2025). "Four of five RAF1-mutant patients developed adolescent-onset cardiac manifestations (dyspnea, palpitations), supporting RAF1-related Noonan syndrome as a differential for hypertrophic obstructive cardiomyopathy." (PMID 41292581, 2025). "In comparison to global trends, our cohort showed a notably high proportion of Noonan syndrome (NS) cases attributed to pathogenic variants in SOS1 and RAF1, with each accounting for 16% of cases." (PMID 41292581, 2025). "Noonan syndrome is a RASopathy caused predominantly by genetic variants encoding the SHP2 protein (e.g., PTPN11, SOS1, RAF1), ultimately leading to hyperactivation of the RAS-MAPK pathway." (PMID 41001496, 2025). "Mutations associated with Noonan syndrome alone include CBL, BRAF, KRAS, LZTR1, MAP2K1 (MEK1), NRAS, PTPN11, RAF1, RIT1, SOS1 and SOS2." (PMID 38550930, 2023). "Somatic pathogenic variants in genes of the RAS/MAPK signaling pathway, in turn, are causative for RASopathies such as Noonan syndrome (BRAF, MAP2K1, PTPN11, or RAF1 variants), Costello syndrome (HRAS variants) as well as other Noonan-like syndromes." (PMID 38835734, 2023). "Noonan syndrome 5 (NS5, OMIM #611553) and LEOPARD syndrome 2 (LPRD2, OMIM #611554) are caused by heterozygous mutations in RAF1." (PMID 32640757, 2020). "The PTPN11 gene is the most implicated gene in Noonan syndrome (61%), followed by SOS1 and RAF1 genes (15 and 6%, respectively)." (PMID 31030682, 2019). "Our study further supports the striking correlation of RAF1 mutations with HCM and highlights the clinical severity of Noonan syndrome associated with a RAF1 p.Ser259Tyr mutation." (PMID 31030682, 2019). "RAF1:c.1173 G > C:p.(R391S) was identified in a mother and son, both of whom exhibited features of Noonan syndrome." (PMID 29402968, 2018). "Pathogenic gain-of-function variants in RAF1—among other genes including PTPN11, SOS1, and KRAS—cause Noonan syndrome." (PMID 30597917, 2018). "Pathogenic mutations were identified in three families (n = 3/33, 9.1%), including mutations in DNAH11, RAF1 and CHD7, which were associated with primary ciliary dyskinesia, Noonan syndrome, and CHARGE syndrome, respectively." (PMID 30359267, 2018). "Four of the proteins are linked to various forms of the Noonan syndrome (CBL, MAP2K1, RAF1 and SOS), 5 to various types of tumors (MAPK1, PRKCQ, ABL1, GRAP2 and RAS) and one to an autoimmune disorder (RASGRP1)." (PMID 28448599, 2017). "Mutations in RAF1, which encodes a protein kinase involved in MAP kinase pathway, cause Noonan syndrome 5 and Leopard syndrome 2 which are completely unrelated to the present cardiac phenotype seen here." (PMID 24972929, 2014). "Other candidate genes highlighted through overlap with results from other studies include: CECR5 in the cat eye syndrome region, RAF1 involved in Noonan syndrome and PPM1K." (PMID 22912587, 2012).